GNA13 (G protein subunit alpha 13)
Diseases named in the same sentence as GNA13 in open-access papers (continued):
Sharing a sentence is not in itself a finding about the gene and the disease.
colorectal cancer (5 papers, 2016 to 2026). A primary or metastatic malignant neoplasm that affects the colon or rectum. "We previously found that GNA13 is an important mediator of the epithelial-mesenchymal transition (EMT) during colorectal cancer metastasis." (PMID 26735177, 2016). "We previously reported that GNA13 could promote colorectal cancer metastasis by triggering the EMT." (PMID 26735177, 2016). "Zhang Z, Tan X, Luo J, Cui B, Lei S, Si Z, Shen L, Yao H. GNA13 promotes tumor growth and angiogenesis by upregulating CXC chemokines via the NF-κB signaling pathway in colorectal cancer cells." (PMID 37724781, 2023).
diffuse large B-cell lymphoma (5 papers, 2021 to 2025). "In addition, palmitoylation of protein GNA13 – a TSG commonly mutated in germinal center B-cell-like diffuse large B-cell lymphoma (GCB-DLBCL) and Burkitt’s lymphoma – was shown to be essential for its protein stability, membrane association and tumor suppressor activity." (PMID 36226054, 2022). "Consistent with this, over 18% of germinal center B-cell-like diffuse large B-cell lymphoma (GCB-DLBCL) patients harbor loss-of-function mutations or homozygous deletions in the GNA13 gene locus." (PMID 33423045, 2021). "In diffuse large B-cell lymphoma (DLBCL), EZH2 and GNA13 variants are observed exclusively in the germinal center B-cell subtype, whereas CARD11, MYD88, and CD79B variants are characteristic of the activated B-cell subtype." (PMID 37601650, 2023). "GNA13, encoding one of the G protein alpha subunits of heterotrimeric G proteins that transduce signals of G protein-coupled receptors (GPCR), is frequently mutated in germinal center B-cell-like diffuse large B-cell lymphoma (GCB-DLBCL) with poor prognostic outcomes." (PMID 33423045, 2021).
colon cancer (3 papers, 2013 to 2022). "Although the detailed functions of miR-182 silencing the GNA13 expression in colon cancer requires further investigation, their data helps support the reliability of our strategy of novel target selection." (PMID 24564330, 2013). "Although the calculation analysis showed that miR-29c was related to the early colon cancer recurrence, miR-29c can inhibit the metastasis of colon cancer by PTP4A and GNA13." (PMID 29262657, 2017).
glioma (3 papers, 2017 to 2021). A benign or malignant brain and spinal cord tumor that arises from glial cells (astrocytes, oligodendrocytes, ependymal cells). "Our analysis implicated multiple Atrx target genes in glioma cell motility, including Gna13, whose direct transcriptional upregulation and downstream signaling through RhoA GTPases promoted mNPC migration." (PMID 29535300, 2018). "We then evaluated the expression of GNA13 protein in primary glioma stem cell (GSC) lines derived from patient tumors." (PMID 29535300, 2018). "According to the analysis, we found that only the downregulation of CDK17, GNA13, PHF21A, and MTHFD2 was closely associated with a decreased overall survival among patients with glioma." (PMID 29362722, 2017). "To assess whether GNA13 might facilitate similar processes in ATRX-deficient human disease, we examined TCGA gene expression data for lower-grade glioma (LGG), focusing our analysis on those tumors harboring an IDH1 or IDH2 mutation." (PMID 29535300, 2018). "Survival analysis found that CDK17, GNA13, PHF21A, and MTHFD2 are closely associated with glioma." (PMID 29362722, 2017). "Taken together, these data firmly implicate GNA13 and downstream RhoA signaling, along with potentially other ATRX-responsive genes, in the process of ATRX-dependent glioma cell migration." (PMID 29535300, 2018). "According to the study, downregulation of CDK17, GNA13, PHF21A, and MTHFD2 can be considered as biomarkers or therapeutic targets for glioma." (PMID 29362722, 2017). "Up to now, the biological functions of CDK17, GNA13, PHF21A, and MTHFD2 in glioma have remained unclear." (PMID 29362722, 2017). "Our analysis confirmed this latter association, while also demonstrating significantly higher levels of GNA13 transcript in IDHmut-noncodel gliomas." (PMID 29535300, 2018). "The results suggested that CDK17, GNA13, PHF21A, and MTHFD2 might play important roles and potentially be valuable in the prognosis and treatment of glioma." (PMID 29362722, 2017).
renal cell carcinoma (3 papers, 2021 to 2022). "Additionally, miR-30b inhibits EMT in renal cell carcinoma by negatively regulating the guanine nucleotide-binding protein subunit alpha-13 (GNA13) protein expression level." (PMID 35291564, 2022).
schizophrenia (3 papers, 2012 to 2022). A major psychotic disorder characterized by abnormalities in the perception or expression of reality. "For example, GNA13, a candidate disease marker of schizophrenia according to GWAS studies, effects brain microstructure and maintenance of the white matter." (PMID 28117656, 2016). "It is indicated that GNA13 is downregulated in prefrontal cortex of schizophrenia brain and may have negative effect on synaptic plasticity by suppression of GNA13-ERK pathway." (PMID 36418457, 2022).
head and neck squamous cell carcinoma (2 papers, 2018 to 2024). A squamous cell carcinoma that arises from any of the following anatomic sites: lip and oral cavity, nasal cavity, paranasal sinuses, pharynx, larynx, and salivary glands. "As such, GNA12 and GNA13 have been shown to be overexpressed in multiple tumor types such as liver, gastric, head and neck squamous cell carcinomas among others." (PMID 38965558, 2024). "GNA13 levels modulate drug resistance and TIC-like phenotypes in patient-derived head and neck squamous cell carcinoma (HNSCC) cells in vitro and in vivo." (PMID 29255247, 2018).
breast invasive carcinoma (1 paper, 2019). "The interactive network shows that SNAPC5, PCBP2 and GNA13 are connected to other frequently altered genes from the TCGA breast invasive carcinoma dataset, which are also selected by other competing methods." (PMID 31534156, 2019).
breast tumor (1 paper, 2015). "To begin to address this question, we performed an analysis of mRNA levels of Pri-miR-31 (primary transcript of miR-31) and GNA13 in 7 normal breast and 41 breast tumor tissues." (PMID 25889182, 2015). "In our screen for the expression of miR-31 and GNA13 mRNA in panel of 41 breast tumor tissues, mRNA levels for miR-31 showed an inverse correlation to those of GNA13." (PMID 25889182, 2015).
depression (1 paper, 2010). "The jointly up-regulated expression of both the phospholipases and GNA12 and GNA13 suggests a relationship between glioblastoma, inflammation, and depression." (PMID 20122237, 2010).
hepatocellular carcinoma (1 paper, 2016). A malignant tumor that arises from hepatocytes. "However, little is known about GNA13 expression and its clinical significance in hepatocellular carcinoma (HCC)." (PMID 27883022, 2016).
Impaired glucose tolerance (1 paper, 2023). An abnormal resistance to glucose, i.e., a reduction in the ability to maintain glucose levels in the blood stream within normal limits following oral or intravenous administration of glucose. "Mice with a liver-specific deletion of Gna13 have been reported to display impaired glucose tolerance and noticeable insulin resistance when fed a high-fat diet, suggesting the involvement of GNA13 in glucose regulatory processes." (PMID 38077141, 2023).
liver cirrhosis (1 paper, 2016). "Based on this analysis, GNA13 expression, tumor size, tumor multiplicity, liver cirrhosis, pathological grades, TNM stage, BCLC stage and vascular invasion were found to impact survival." (PMID 27883022, 2016). "We observed that GNA13 expression, pathological grades and tumor size were independent prognostic factors for OS, whereas GNA13 expression, as well as pathological grades and liver cirrhosis, were independent prognostic factors for DFS." (PMID 27883022, 2016).
melanoma (1 paper, 2023). A malignant, usually aggressive tumor composed of atypical, neoplastic melanocytes. "GNA13 regulatory regions were upregulated in metastatic SKCM; GNA13 is associated with proliferation and metastasis in several tumour types, but its specific role in melanoma is less understood." (PMID 37914932, 2023).
metabolic dysfunction-associated steatotic liver disease (1 paper, 2024). Metabolic dysfunction-associated steatotic liver disease (MASLD, formerly known as nonalcoholic fatty liver disease or NAFLD) is a type of liver disease that is not caused by alcohol. "Finally, we assessed hepatic gene expression levels of GNA12 and GNA13 using liver biopsy samples obtained from human subjects with metabolic dysfunction-associated steatotic liver disease (MASLD; n = 24)." (PMID 39557854, 2024).
neuroblastoma (1 paper, 2021). Neuroblastoma (NB) is the most common solid, extracranial childhood tumor. "PPM1D, GNA13, and STAT family genes – all on 17q and implicated in up to 70% of neuroblastomas – showed the strongest correlations of copy number and cytotoxicity to targeted inhibitors." (PMID 34722256, 2021). "PI3Kα inhibitor PIK-75 (78.9% cytotoxicity) stimulates anti-neuroblastoma activity by destabilizing MYCN and sensitizing tumor cells to anthracyclines, and indeed increased cytotoxicity with PIK-75 was associated with PPM1D and GNA13 gain, and DNMT3A, CBL, EED and ASXL2 loss." (PMID 34722256, 2021).
osteoporosis (1 paper, 2017). A condition of reduced bone mass, with decreased cortical thickness and a decrease in the number and size of the trabeculae of cancellous bone (but normal chemical composition), resulting in increased fracture incidence. "Osteoclast-lineage-specific Gna13 conditional knockout mice have a severe osteoporosis phenotype." (PMID 28102206, 2017).
ovarian carcinoma (1 paper, 2022). A malignant neoplasm originating from the surface ovarian epithelium. "This study also reported an analysis of publicly available tumor gene expression databases showing that GNA13 mRNA was upregulated in many solid tumors, and patients with higher GNA13 expression showed significantly poorer overall survival in breast, lung, gastric, and ovarian cancers." (PMID 34689178, 2022).
pancreatic cancer (1 paper, 2023). "For example, GNA12 together with GNA13 promotes gastrin-induced directional migration of pancreatic cancer cells via the cholecystokinin B receptor-GNA12/13-RhoA-ROCK signaling pathway." (PMID 37426201, 2023).
renal carcinoma (1 paper, 2021). A carcinoma arising from the epithelium of the renal parenchyma or the renal pelvis. "As a tumor suppressor, miR-30b-5p regulates the proliferation, metastasis, and EMT of renal cancer cells by down-regulating the expression of GNA13." (PMID 34819077, 2021).
tumor (34 papers, 2006 to 2025). "Loss of GNA13 expression drives cell proliferation, soft-agar colony formation and in vivo tumor formation in an orthotopic xenograft model." (PMID 38965558, 2024). "According to a recent study, GNA13 expression is associated with drug resistance and tumor-initiating phenotypes in HNSC." (PMID 36186458, 2022). "Meanwhile, analyzing the genome of tumor tissues from patients with classical Hodgkin lymphoma has revealed that GNA13 is one of the genes repeatedly mutated." (PMID 35237598, 2022). "Our data further support the idea that GNA13 plays tumor suppressor function in germinal center B cells and loss-of-function mutations of GNA13 are involved in lymphomagenesis." (PMID 33423045, 2021). "To examine the role of palmitoylation in GNA13’s tumor suppressor function, we compared the tumor suppressor activity of palmitoylation-deficient mutants of GNA13 to that of WT counterpart in two GCB-DLBCL cell lines." (PMID 33423045, 2021). "Although we observed that high expression of GNA13 in HCC was closely implicated in tumor progression, further investigation is needed to fully elucidate the precise mechanisms of GNA13 involved in the metastasis and progression of HCC." (PMID 27883022, 2016). "GPCRs signal primarily through heterotrimeric G proteins; and among the different types of G proteins, GNA12 and GNA13 have been particularly associated with tumor progression." (PMID 26735177, 2016). "Recurrent mutations in the GNA13 gene have been identified in multiple tumor types." (PMID 33423045, 2021). "However, the risk of neoplasia or haematological malignancy in patients with GNA13 mosaicism is unknown." (PMID 39966435, 2025). "GNA13 promotes tumor cell invasion and metastasis by activating the RhoA/ROCK signaling pathway and the GPCR, BC regulation by Stathmin1, and Estrogen Pathway." (PMID 40149317, 2025). "A study on HNSCC has demonstrated that GNA13 promotes the aggressive phenotype and drug resistance of tumor-initiating cells through the MAPK/AP-1 and NF-κB pathways." (PMID 35237598, 2022). "Consistent with our finding that palmitoylation of GNA13 is required for its tumor suppressor function, at least two DLBCL patients were found to bear the GNA13 C14S mutation." (PMID 33423045, 2021). "We found that two independent GNA13 shRNAs, shGNA13600 and shGNA13UTR, both promoted proliferation of OCI-LY1 cells, supporting the assumption that OCI-LY1 cells retain partial GNA13 tumor suppressor functions." (PMID 33423045, 2021). "Jude Cloud37, we found that there were at least two patients harboring the GNA13 C14S mutation 38,39, suggesting that palmitoylation of GNA13 regulates its tumor suppression function." (PMID 33423045, 2021). "The three GNA13 palmitoylation mutants, on the other hand, did not inhibit proliferation of OCI-LY1 cells, indicating that palmitoylation of GNA13 is required for its tumor suppressor function." (PMID 33423045, 2021). "Consistent with the tumor suppressor function of GNA13, we found that ectopic expression of GNA13WT markedly suppressed proliferation of OCI-LY1 cells." (PMID 33423045, 2021). "Consistent with the previous finding that palmitoylation of GNA13 is required for its tumor suppressor function, ectopic expression of palmitoylation mutants of GNA13 were found to be incapable of suppressing the expression of BCL2 in SU-DHL4-shGNA13UTR cells." (PMID 33423045, 2021). "Here, we show that palmitoylation of GNA13 also regulates its stability and is required for its tumor suppressor function in GCB-DLBCL cells." (PMID 33423045, 2021). "Taken together, these data indicate that GNA13 expression is a potential prognostic biomarker for tumor progression, and that interfering with GNA13-induced signaling provides a novel strategy to block TICs and drug resistance in HNSCCs." (PMID 29255247, 2018).
tumor (continued). "In contrast, injection with 5 × 105 NCC-HN43 cells that stably express either shRNA-control or shRNA-GNA13 in NOD/SCID mice showed a significant reduction in tumor sizes in GNA13-knockdowns as compared to controls." (PMID 29255247, 2018). "NCC-HN26 cells expressing GNA13 initiated tumor growth significantly earlier as compared to vector control cells, leading to significant increase in tumor size at the end of 61 days." (PMID 29255247, 2018). "Targeting GNA13 by silencing its expression reversed the tumor initiation and drug resistance in HNSCC cancer cells and in tumors." (PMID 29255247, 2018). "GNA13, one member of the G protein family, is involved in metastasis of tumor cells, angiogenesis, and cellular responses to chemokines." (PMID 29362722, 2017). "Further study showed that upregulation of GNA13 expression increased the proliferation and tumorigenicity of GC cells in vitro and in vivo, by promoting cell growth rate, colony formation, and tumor formation in nude mice." (PMID 26735177, 2016). "Our analyses showed significant correlations between GNA13 expression and three characteristics including tumor multiplicity (P = 0.004), TNM stage (P = 0.002) and BCLC stage (P = 0.010)." (PMID 27883022, 2016). "High GNA13 expression was also strongly correlated with clinical stage, T status, N status, and tumor size in two GC cohorts (P < 0.05)." (PMID 26735177, 2016). "Based on the subgroup analysis, GNA13 predicted the clinical outcome of the following subsets of HCC patients: tumor size > 5 cm, TNM stage III/IV, and pathological grade III/IV." (PMID 27883022, 2016). "The tumor samples with high levels of GNA13 staining also exhibited strong Ki-67 staining signals, whereas areas with low GNA13 expression exhibited weak Ki67 expression." (PMID 26735177, 2016). "It is essential for the tumor suppressor function of GNA13 in GCB-DLBCL cells." (PMID 33423045, 2021). "Moreover, we deployed survival analysis towards the level of GNA13 expression in subgroups of HCC patients against tumor size, TNM stages, and histological grades." (PMID 27883022, 2016). "Consequently, we hypothesized that GNA13 might induce a tumor initiating or stem cell-like phenotype in these cancer cells." (PMID 29255247, 2018). "Thus, miR-29c could serves as a tumor metastasis suppressor, which negatively controls the cancer metastasis via targeting many molecules including Sp1, GNA13, PTP4A, integrin β1 and MMP2." (PMID 27829234, 2016). "Different Ga protein families have different functions in the occurrence and development of tumors, such as GNA12 and GNA13, which belong to the GNA12/13 family and play a role in promoting oncogenic transformation and tumor cell growth." (PMID 33500727, 2021). "Crucially, our findings convincingly demonstrate that blocking GNA13-induced MAPK/AP-1 and/or NFκB signaling can indeed be a strategy to target TIC-induced tumor growth and therapeutic resistance in solid tumors that express high amounts of GNA13." (PMID 29255247, 2018). "Immunohistochemical analysis of the tissue micro array derived from these patients established the functional correlation between the decreased expression of tumor suppressive miRNAs and their target oncogenes: ERBB2, EGFR, EPHA2, BAX, GNA12, GNA13, and JUN." (PMID 28740575, 2017). "In our study, GNA13 was reported to be significantly up-regulated in HCC tissues, and this was correlated with several clinicopathological parameters, including tumor multiplicity (P = 0.004), TNM stage (P = 0.002), and BCLC stage (P = 0.010)." (PMID 27883022, 2016). "Additionally, survival analysis showed that GNA13 expression could significantly stratify OS in a subset of GC patients with different age, gender, T status, N status, M status, overall clinical stage, tumor grade and tumor size (P < 0.05)." (PMID 26735177, 2016). "Notably, silencing GNA13 in PC3 cells significantly reduced tumor growth rate and tumor weight by approximately 40%." (PMID 40430023, 2025).